PARP1 (poly(ADP-ribose) polymerase 1)
Diseases named in the same sentence as PARP1 in open-access papers (continued):
Sharing a sentence is not in itself a finding about the gene and the disease.
tumor (continued). "Furthermore, resistant/relapsed tumours do not show substantial changes in PK/PD of olaparib, do not downregulate PARP1 or re-establish double stranded DNA break repair by homologous recombination, all previously suggested as mechanisms of resistance." (PMID 31080552, 2019). "In addition, allelic imbalances of PARP1 and TGFB2 were detected in the tumor of the proband." (PMID 30680959, 2019). "Based on the theory that PARP overexpression is largely neoplasia-specific in adults, we hypothesized that radiation injury would not present with elevated levels of PARP1 expression." (PMID 29974335, 2018). "The PARP1/2 imaging agent [18F]PARPi is therefore well suited to image in PARP1-expressing tumors, quickly clearing from non-target tissue while binding strongly to tumor over the course of 2 h resulting in a tumor/muscle ratio of 7.6 ± 2.7 in JHU-LX48 bearing animals (P = 0.0072)." (PMID 29330466, 2018). "PARP-1 is involved in many cellular processes (e.g. DNA repair, genomic stability, inflammation, differentiation, cell death) and it has been shown that PARP-1 inhibition targets hypoxia-mediated repair defects in tumor cells and it reduces vasculogenic mimicry." (PMID 29152107, 2017). "However, PJ34 treatment inhibited PARP-1, improved the hepatic enzymes, and decreased the engraftment rates of tumor cells compared to mice which suffered from the same ischemic time without PARP-1 inhibition." (PMID 29179487, 2017). "Protein levels of PARP-1 and poly(ADP-ribose) (PAR) were significantly increased in the combination group compared to the control, and those of VEGF and MDR1 were significantly reduced in the combination group, which was consistent with inhibition of tumor growth in vivo." (PMID 26927065, 2016). "Specificity of the staining became obvious in higher magnifications, where it could be seen that only tumor cell nuclei displayed strong PARP1 staining, but not stromal tissue or muscle tissue." (PMID 26808835, 2016). "Differentially expressed genes with PARP-1 inhibition were mainly enriched in regulation of transcription, metabolic process, cell proliferation, apoptotic process, and phosphorylation, which supports PARP-1 function in inflammation, tumor, and metabolic disorders." (PMID 26314963, 2015). "PARP1 inhibitors do not always have a direct cytotoxiceffect on tumor cells." (PMID 26483957, 2015). "Taken together, we suggest that tumor-suppressive effect of PARP1 inhibition is mediated, at least in part, by FOXO3A activation, although further studies might be required to address direct signaling mechanisms between PARP1 and FOXO3A." (PMID 26540566, 2015). "We would therefore predict that MMe tumours lacking expression of BRCA1 might also represent a molecularly defined subgroup of tumours with sensitivity to PARP1 inhibition." (PMID 23301673, 2013). "However, a comprehensive analysis of PARP-1 activity, BRCA1 promoter methylation and 53BP1 expression in tumours without known BRCA1 mutation has not yet been carried out." (PMID 24191908, 2013). "In addition, PARP-1 and its interaction with the cell cycle control protein p21 (CDKN1A) may also contribute to tumorigenesis and the tumor phenotype." (PMID 24202328, 2013). "Additionally, in the preclinical setting, the use of PARP-1 inhibitors as single agents did not cause any measurable toxicity, but the combination of PARP-1 inhibitor with temozolomide in the tumor-bearing mice caused significant toxicity." (PMID 20049345, 2010). "Furthermore, Western blot analysis of excised HeLa tumor tissues demonstrated the overexpression of MCPIP1 in tumors treated with SLpMCPIP1 (+), and SLpMCPIP1 (+) further reduced XIAP but increased the expression of cleaved caspase-3 and cleaved PARP1 proteins compared with SLpEmpty (+) treatment." (PMID 39408613, 2024).
tumor (continued). "Interestingly, mechanism study revealed that AKT inhibition decreased PARP enzyme activity as measured by PAR level and/or reduced PARP1 protein level in the tumor cell lines and PDX tumor tissues, which may explain the observed combined anti-tumor effect of LAE003 and Olaparib." (PMID 35419627, 2022). "Notably, when cultured in the tumor‐on‐a‐chip system, a significant number of MDA‐MB‐436‐PARP1m underwent apoptosis without the addition of chemotherapeutic drugs, showing a similar fate of PARP1 inhibitor monotherapy found in preclinical and clinical validations." (PMID 31989039, 2020). "A recent study used a modified proximity ligation assay to detect chromatin-trapped PARP1 and concluded that PARP1 trapping correlated with cellular toxicity in both non-malignant and tumor cells, which may limit the therapeutic advantage of potent trapping activity." (PMID 33015058, 2020). "The trapping of PARP1 and DNMT1 to chromatin, acetylation of DNA repair proteins, and down-regulation of NuRD may all have increased double-strand DNA break (DSB) formation as suggested by activation of the DNA-damage response, concomitantly resulting in tumor cell death." (PMID 29423093, 2018). "However, whether the effect of prolonged PARP-1 inhibitor exposure leads to a reciprocal modification of the tumour microenvironment has not been studied." (PMID 29152107, 2017). "To exclude the possibility of an increase of nonspecific staining after irradiation we chose a tumor that was irradiated with 10 Gy 48 hours prior to PARPi-FL staining, and found a specific localization of the PARPi-FL signal in nuclei (Hoechst staining) which express PARP1." (PMID 26808835, 2016). "We measured iNOS mRNA expression in paired tumor and non-tumor tissues of a cohort of 186 CRC patients previously used to evaluate the prognostic implication of PARP-1 in CRC." (PMID 39858519, 2025). "Combining plant-derived sphingosine and γ-radiation can enhance the death of radioresistant tumor cell lines through the nuclear translocation of AIF in response to ROS-mediated Bax relocation and the activation of PARP-1 independent of ROS." (PMID 37351512, 2023). "Since blocked replication forks cannot be restarted without the help of PARP1/2, SSB inevitably lead to more severe DSB; hence, tumor cells lacking active BRCA1 or BRCA2 are sensitive to a PARP inhibitor molecule." (PMID 37569269, 2023). "However, it is important to mention that the tumour was platinum resistant and did not harbour gBRCAm (or mutations in other DDR genes), which could be the main reason driving olaparib resistance in this case, regardless of PARP1 status." (PMID 35008208, 2021). "We, therefore, aimed to assess the presence of PARP1 and SLFN11 protein expression in clinically derived tumor tissue of UV AS and non-UV AS cases." (PMID 34085099, 2021). "For example, PARP-1, but not PARP-2, is involved in the formation of immunosuppressive macrophage phenotypes in the tumor microenvironment after olaparib treatment and further modulate immunosuppression by enhancing PD-1 expression." (PMID 33525353, 2021). "This means new treatments can be tested on these non-responsive tumours in vitro like non-cisplatin compounds, including inhibitors of the PI3K/AKT/mTOR pathway, Poly(ADP-Ribose) Polymerase 1 (PARP), the tyrosine kinase, Wee1 and gemcitabine." (PMID 33580825, 2021). "Accurate quantification of tumor cell density was not possible because there are no validated tumor cell markers for IDH wild type GBM, but the surrogate tumor markers PARP-1 and Ki67 supported the histological evaluation." (PMID 32347934, 2020). "Even though high plasma protein binding (96.2%) is tolerable for imaging of primary tumor due to BBB disruptions, it is not optimal for PARP1 imaging of metastasis with an intact BBB." (PMID 32640708, 2020).
tumor (continued). "However, in this study, we wished to determine whether repetitive administration of a PARP-1 inhibitor (olaparib) prior to radiotherapy (i.e. strictly neoadjuvant, rather than concurrent, olaparib treatment) could improve tumour oxygenation prior to radiation treatment." (PMID 29152107, 2017). "Although PARP1 expression was increased in both grade III and IV tumours, there were no significant changes between those two grades." (PMID 28654422, 2017). "Compared to PARP1, the mechanism of PARP11 in tumor development has not been uncovered." (PMID 39949782, 2025). "Moreover, PARP1 and PARP2 expression were lower in tumor subsets with high Aneuploidy score, although the correlation with LST and FGA did not achieve statistical significance for PARP1 and PARP2, respectively." (PMID 40573300, 2025). "The CDA-dextran conjugates strongly reduce the tumor size and weight of the Ehrlich cells (EAC), dramatically increase the titers of Caspase-independent apoptotic markers PARP-1 and AIF, with no cellular cytotoxic activity, as revealed from the hematological and biochemical parameters." (PMID 36627557, 2023). "In both cases, significant tumor growth inhibition was observed, regardless of whether they were responsive (HOC106) or not (HOC107) to the first-generation dual PARP1/2 inhibitor olaparib." (PMID 36994441, 2023). "Of note, the PARP1-dependent absence of NKG2D-L on acute leukemia cells correlated with cancer stem cell properties, supporting immune evasion of these stem cells and finally leading to tumor development." (PMID 37143070, 2023). "This transformation is not dependent on PARP1 or PARP2 but is the result of the accumulation of the PARP substrate NAD+, which allows for increased mitochondrial RET, resulting in ROS production and reprogramming toward an anti-tumor phenotype." (PMID 36223740, 2022). "Of note, inhibition of PARP-1 has been shown to promote NKG2D ligands expression on LSCs, without affecting their expression on non-stem tumor or normal hematopoietic cells in a preclinical AML mouse model, providing a rationale to combine PARPi and NK cell-based immunotherapy for AML treatment." (PMID 36428727, 2022). "The tumors expressing PARP1 without counter-balanced FOXO3A expression (i.e., FOXO3A−/PARP1+) might acquire uncontrolled tumor growth provoking aggressive behavior." (PMID 26540566, 2015). "Moreover, HRD scores may not fully capture the context in which PARP1 and PARP2 protect the CRC genome against worsening genotoxic stress, nor the contexts in which their inhibition would be beneficial for tumor cell killing." (PMID 40573300, 2025). "Similar to other studies, in this work we found PARP-1 was overexpressed in CRC samples compared to their healthy mucosa, however, in our cohort, the expression of PARP-1 was correlated to differentiation grade, specifically with dedifferentiated tumours, and not with tumour progression." (PMID 36902215, 2023). "Moreover, a cross-talk between PARP1 and androgen receptor (AR) function has been proposed as the basis of the benefit of the combination of PARPi with AR inhibitors regardless of the HRD status of the tumour." (PMID 35008208, 2021). "Collectively, these results provide new evidence that these three factors (Lig3, Lig1, and PARP1) have a functional role in MYCN oncogenic activity in human NCSC, and sets precedence to investigate alt-NHEJ and non-canonical DNA repair factors in NBL tumor initiation and progression." (PMID 29238067, 2017). "Top2 and PARP1 play overlapping roles to Top1 in non-dividing cells suggesting that the combination of Top1,Top2 and PARP-targeting drugs may be effective in non-dividing tumor cells." (PMID 24194914, 2013).
infection (76 papers, 2007 to 2026). The state of being infected such as from the introduction of a foreign agent such as serum, vaccine, antigenic substance or organism. "Severe depletion of NAD+ during most pathogenic infections mainly arises due to targeted over-activation of PARPs, (primarily PARP-1)." (PMID 34485381, 2021). "Owing to its association with the virion, vPIP is likely to modulate PARP1 function during the early phase of de novo infection." (PMID 35095818, 2021). "PARP-1 has been implicated in the infection and pathogenesis of several viruses." (PMID 36146855, 2022). "The DNA repair function could indirectly contribute to fighting infection as reactive oxygen species (ROS) could induce DNA damage, thus having PARP1 active is important under increased oxidative stress caused by infections." (PMID 34871367, 2021). "Inhibiting PARP-1 might increase the susceptibility to infection based on the immunostimulatory role of PARP-1." (PMID 33178190, 2020). "Secreted PARP1 and 8-OHdG levels were increased by 6.5- to 7.0-fold and 1.4- to 1.9-fold, respectively, in C/A and C/S subjects (versus N/H; P < 0.001) and exhibited strong association as independent predictors of occurrence of infection (AUC ≥ 0.99; PARP1 R2C&S = 0.698; 8-OHdG R2C&S = 0.682)." (PMID 34479416, 2021). "Oxidative stress or infection could induce PARP1 overactivation, causing DNA damage." (PMID 33482196, 2021). "Consistently, infection with Ad-PARP1 also suppressed myocardin or myocardin–SRF overexpression-induced 6×CArG-drove luciferase activity." (PMID 40744995, 2025). "In a model of intraperitoneal vaccinia virus (VV) infection, PARP1 recruits NK cells to the site of infection, through the CCL2-CCR2 axis, thereby facilitating viral control." (PMID 41460301, 2025). "This was confirmed by the fact that infection with Ad-PARP1 reversed myocardin overexpression-induced reduction in luciferase activities driven by WT-CyclinD1, WT-MMP9 promoter and 6×AP1." (PMID 40744995, 2025). "This review will focus on the role of PARPs, particularly PARP1, in regulating the infection of DNA viruses." (PMID 38392869, 2024). "PARP-1 promoted the migration of natural killer (NK) cells to the site of infection, via NF-κB-mediated production of CCL2 by macrophages." (PMID 39201718, 2024). "In conclusion, we showed that in a mouse model of Pm infection, GA significantly reduced Pm-induced vascular inflammatory injury, and decreased PARP1, HMGB1, IL-1β, and IL-18 protein expression in vascular tissue." (PMID 39850582, 2024). "Given the dual roles of PARP1 as a DNA damage sensor and a mediator of inflammation and regulated cell death, PARP1 participates in the host immune defense against E. piscicida’s infection." (PMID 38332126, 2024). "In this study, we identified a T3SS effector, named YfiD, to rescue PAR accumulation and PARP1-dependent cell death driven by E. piscicida’s infection." (PMID 38332126, 2024). "The bacterial T3SS effector YfiD interacts with the catalytic domain of host PARP1 during infection." (PMID 38332126, 2024). "The data implicating PARP-1 in provirus integration have been less clear, with reports implicating PARP-1 in HIV provirus integration, while other studies suggest that PARP1 is dispensable for infection." (PMID 38793632, 2024). "The 16K-induced nucleolar relocalisation of coilin occurring upon TRV infection results in an increase in the nucleolar retention of PARP1, thereby preventing it trafficking from the nucleolus to CBs for PAR cleavage and recycling." (PMID 37376582, 2023). "Following sgRNA infection, cells are treated with olaparib, a potent PARP1 inhibitor, and only cells harboring a sgRNA that deregulates the homologous recombination DNA damage repair pathway are rendered sensitive to olaparib." (PMID 36991492, 2023).
infection (continued). "Jointly, our data show that PARP1-facilitated dsDNA repair is engaged in the initial stages of infection, and the NHEJ mechanism determines the HTJ format of the earliest hepadnavirus–host genomic merges." (PMID 37834296, 2023). "In COVID samples, Patel was able to demonstrate a significant difference in the levels of PARP1 in critical disease states of infection." (PMID 36499104, 2022). "In the present study, our results showed that infection with S. aureus increased the cytotoxicity and the protein expression of Bax, caspase-3, and cleaved-PARP-1 in goat endometrial epithelial cells (gEECs)." (PMID 35327108, 2022). "Nevertheless, we found a significant reduction of caspase-9 and a significant increase of 89 kDa PARP-1 fragment after infection." (PMID 35765029, 2022). "At the early stages of infection, western blotting revealed that PARP1 is, in fact, targeted to the chromatin of infected cells 1 h (1.85 fold change) and 6 h (2.40 fold change) after infection." (PMID 33826673, 2021). "PARP1 also decreases interferon alpha/beta receptor (IFNAR) expression upon infection by influenza A virus (IAV) or overexpression of IAV hemagglutinin (HA)." (PMID 34871367, 2021). "This study investigated PARP-1 activation in leukocyte subpopulations from bovine milk samples during udder infection." (PMID 33803196, 2021). "The authors evidenced that PARP1 KO mice display a reduction in parasite load and that PARP1/PAR affects mitochondrial integrity during infection." (PMID 33826673, 2021). "Overexpression of PARP1, which occurs under oxidative stress or infection, also inhibits gap-filling activity." (PMID 33482196, 2021). "Expression of Parp1 mRNA changed little, but mRNAs for Parp9, -10, -12, -13, and -14 were increased by infection." (PMID 32047134, 2020). "Experiments in cell culture infections showed a >50% reduction in infectious IAV titer released from cells depleted of PARP1 by RNAi." (PMID 31015836, 2019). "When PARP1 was targeted by siRNA, expression of viral NP during infection of human lung A549 cells with low-path, avian-derived influenza virus strain A/Viet Nam/1203/04 (H5N1) HALo was considerably reduced." (PMID 31015836, 2019). "Early during infection, viral genomes also associate with factors that have known roles in the recognition or processing of DNA breaks, including RPA1, PARP1, PARP14, and ligase 3 (LIG3)." (PMID 30018111, 2018). "We then evaluated the effect of Tc infection on the levels of PARP1 mRNA, protein, and activity in WT and PARP1-/- mice." (PMID 29851986, 2018). "In contrast, infection with the Ad-PARP1-RNAi virus before GO treatment downregulated the expression (P < 0.01)." (PMID 26526840, 2016). "PARP-1 is present in the native and cleaved state in infected and treated cells at 24, 48 and 72 h post-infection." (PMID 25614100, 2015). "For instance, an interaction between PARP1 and p65 is correlated with Cd11a expression in experimental models of ischemia-reperfusion and infection." (PMID 25161822, 2014). "Moreover, infection with shc-Jun versus scramble shRNA abolished PARP1 overexpression-induced expression of CyclinD1, Pcna, Mmp9 and Mmp2 genes, as well as the increase in the neointima/media ratio of balloon-injured arteries." (PMID 40744995, 2025). "In experiments of PARP1 gain of function, infection with Ad-PARP1 versus Ad-Null increased cell numbers, EdU incorporation, wound closure and transwell migration of wt-mVSMCs under PDGF-BB treatment, indicating that gain of PARP1 promoted VSMC proliferation and migration." (PMID 40744995, 2025). "A few studies have established the connection between PARP1-dependent cell death and infection." (PMID 38332126, 2024). "Importantly, an 18-fold reduction in CCL2 levels was identified in PARP-1 knockout mice in the setting of infection." (PMID 39201718, 2024). "Following infection of E. piscicida lacking yfiD in macrophages, internalized bacteria-caused DNA lesion is recognized by PARP1 followed by its self-activation." (PMID 38332126, 2024).